TNF (tumor necrosis factor)
Diseases named in the same sentence as TNF in open-access papers (continued):
Sharing a sentence is not in itself a finding about the gene and the disease.
tuberculosis (continued). "However, in terms of tuberculosis, TNF inhibitors significantly increased the risk of infection compared to placebo (OR:2.21, 95%CI:1.05–4.66)." (PMID 39070789, 2024). "In contrast to the numerous cases of tuberculosis reactivation during TNF-α inhibitor treatment and a few cases linked to IL-12/23 inhibitors, there have been no reported instances in patients exposed to IL-23 or IL-17 inhibitors in both clinical and real-world settings, aligning with our findings." (PMID 38392619, 2024). "On the other hand, one must highlight that the occurrence of granulomatous infections, such as tuberculosis, and fungal infections, mainly by Candida, characterizes a special situation associated with the inherent mechanism of the anti-TNF and anti-IL17 classes, respectively." (PMID 38238209, 2024). "Additionally, etanercept slightly affects membrane-bound TNF, with a lower risk of tuberculosis compared with monoclonal antibodies." (PMID 39070789, 2024). "TNF induces pathogenic mitochondrial reactive oxygen species (ROS) in tuberculosis." (PMID 39046230, 2024). "The five TNFα inhibitors showed similar efficacy profiles, although recent data show that adalimumab seems to be most effective in geriatric patients, while etanercept is associated with a lower risk of developing tuberculosis." (PMID 37554981, 2023). "Furthermore, the use of tumor necrosis factor-alpha (TNFα) inhibitors (TNFis) increases the risk of infection, including tuberculosis (TB) and hepatitis B virus." (PMID 36909171, 2023). "However, the adverse reactions of hepatotoxicity and gastrointestinal limit the clinical use of MTX, and its combination with TNF-α mab increases the risk of reactivation of tuberculosis." (PMID 35814239, 2022). "These DEGs were highly clustered in several inflammation-associated signaling pathways, such as the TNF signaling pathway, cytokine-cytokine receptor interaction, tuberculosis, human T-cell leukemia virus 1 infection, the FoxO signaling pathway, malaria, and cell adhesion molecules." (PMID 34552216, 2022). "Blocking TNF-α signaling disrupts the formation of this granuloma by reducing proinflammatory signals, leading to apoptosis of immune cells maintaining this granuloma, thus allowing the entrapped M. tuberculosis to escape and cause active tuberculosis." (PMID 36159650, 2022). "In addition, a meta-analysis also showed a significantly increased risk for tuberculosis occurrence (odds ratio = 1.94, 95% CI 1.10–3.44) in TNF inhibitor users." (PMID 36430392, 2022). "Reports show that patients treated with anti-TNF-α agents are at high risk of tuberculosis." (PMID 36362709, 2022). "However, long-term use of anti-TNF-α agents has also been reported to be closely associated with increasing risk of adverse events like serious infections, malignancies, skin, tuberculosis, and cancer." (PMID 35340587, 2022). "Tuberculosis is a very common infectious disease in Brazil (estimated prevalence, 104 per 100,000 patient-years) leading to serious public health problems, and therefore the use of anti-TNF-α would further potentiate the risk of infection in this region." (PMID 36362709, 2022). "The risk of tuberculosis was lower in etanercept users than in users of monoclonal antibody forms of TNF inhibitors in Asia, which may arise from the relatively low affinity of etanercept for TNF-α compared with the monoclonal antibody forms of TNF inhibitors." (PMID 36430392, 2022). "However, long-term use of anti-TNFα agents has been associated with the risk of serious infections, malignancies, skin and soft tissue infections, and tuberculosis." (PMID 34790122, 2021). "Children with rheumatic disorders might be predisposed to Tuberculosis due to the intrinsic mechanism of action of biologics, anti-TNFs in particular, as they target TNF-α, the key cytokine for the Th1 axis." (PMID 35128322, 2021).
tuberculosis (continued). "Tuberculosis is associated with both lung squamous cell carcinoma and adenocarcinoma, leading to the release of inflammatory mediators such as IL-1, IL-2, and IL-12; tumor necrosis factor alpha (TNF-α); and INF-γ, which induce the inflammation of lung tissues." (PMID 34502312, 2021). "Moreover, this has also been confirmed in the mouse models where TNF-α gene-deficient mice were infected with tuberculosis pathogens to study the role of TNF-α in tuberculosis infection." (PMID 34776944, 2021). "Because it has been demonstrated that patients receiving TNF antagonists are at a higher risk of developing tuberculosis, we evaluated the expression of members of the TNF pathway on CD3+ MDMs infected with virulent and avirulent Mtb strains and observed differences associated with virulence." (PMID 35008755, 2021). "Another study that investigated the effect of ginger on inflammatory markers among patients treated for tuberculosis found the use of ginger to be associated with a significant reduction in the level of inflammatory markers, such as tumor necrosis factor-alpha (TNF-α) and ferritin." (PMID 34064950, 2021). "Besides, the risk of tuberculosis was higher for anti-TNFα antibody in axial SpA (Peto OR: 6.17, 95%CI: 1.03–37.13, p = 0.046)." (PMID 34776944, 2021). "The increasing risk of tuberculosis is a main safety issue for anti-TNF-α therapy." (PMID 34776944, 2021). "Importantly, TNF, which has been implicated in the pathogenesis of tuberculosis, including tuberculous meningitis, appears to be dysfunctionally increased both in an LTA4H-independent and -dependent manner." (PMID 33658385, 2021). "Additionally, biologic therapies such as tumor necrosis factor-α (TNF-α) antagonists (monoclonal antibodies or soluble receptors) can increase the risk of opportunistic infections such as tuberculosis." (PMID 32258176, 2020). "In addition to the assumed pathogenic role of IL10 in tuberculosis disease progression, the protective roles of the pro-inflammatory cytokines TNFα and IL1β have been well documented by in vivo murine models, and for IL1β in hMDMs." (PMID 32477344, 2020). "Interestingly, clinical observations revealed that the risk of tuberculosis reactivation is associated with anti-TNF-α treatment but also depends on the type of anti-TNF-α agent." (PMID 31475008, 2019). "Evidence suggests TNF-a gene is associated with the development of tuberculosis." (PMID 31072917, 2019). "In addition, an appropriate TNF level has been shown to be important for tuberculosis immunity, as both the deficient and excessive production of TNF are linked to accelerated pathogenesis." (PMID 29985419, 2018). "However, patients treated with TNF inhibitors are at increased risk of developing tuberculosis, predominantly through the reactivation of latent tuberculosis infection (LTBI)." (PMID 29975703, 2018). "In addition, the number of published articles on TNF −308 (rs1800629) gene polymorphisms in CD is low compared to studies on other chronic infectious diseases such as tuberculosis, for which more than 15 studies were available." (PMID 29768622, 2018). "Furthermore, among others, SNPs in Interleukin 1β (IL1B), IL12, IFNG, Interleukin 10 (IL10) and Tumor Necrosis Factor α (TNFα) genes were described in relation with risk to tuberculosis disease." (PMID 29361774, 2018). "The inhibitory effect of anti-TNF-α therapy on autophagy may be responsible for its associated increase of infection risk, particularly tuberculosis." (PMID 30518408, 2018). "However, considering the well-known risk of tuberculosis with anti-TNF therapy, it is surprising that only 90% screened for tuberculosis." (PMID 30009157, 2018). "Moreover, the most frequently prescribed TNF inhibitor of our study subjects was etanercept, which is known to have a lower risk of tuberculosis than anti-TNF monoclonal antibody." (PMID 29975703, 2018).
tuberculosis (continued). "Interestingly, anti-TNF antibodies such as infliximab and adalimumab invoke significantly greater risk of active tuberculosis in man, than the soluble TNFR, ETN." (PMID 28824652, 2017). "Likewise, the use of anti-TNF antibodies incurs significantly greater risk of active tuberculosis than that of ETN." (PMID 28824652, 2017). "Consequently, increased risk of tuberculosis associated with anti-TNF therapy is also widely interpreted to be due to deficient TNF activity in cell-mediated immune protection, but direct evidence for this is lacking." (PMID 28824652, 2017). "Fifty-six AS patients were treated for tuberculosis associated with TNF inhibitors." (PMID 27101309, 2016). "Sensitivity to the anti-tuberculosis drug should then be confirmed, and drug compliance and the formation of cavities, which are factors associated with treatment failure, should be carefully monitored during maintaining reintroduced TNF inhibitors." (PMID 27101309, 2016). "Although the precise mechanism by which infliximab increases susceptibility to tuberculosis is not yet fully understood, TNF-alpha is known to be involved in the recruitment of inflammatory cells, macrophage activation, granuloma formation, and disease containment." (PMID 27366159, 2016). "Indeed, several articles showed that anti-IL-1 agents, such as anakinra, are safe in comparison with other biotherapies, such as anti-TNF-alpha, considering the risk of tuberculosis reactivation." (PMID 25922564, 2015). "Importantly, the clinical experience with canakinumab differs from that of TNF-α blockers which are associated with an increased risk of tuberculosis reactivation." (PMID 24884602, 2014). "The median interval between starting infliximab and the development of infection was only 12 weeks; this finding supports the contention that the use of this TNF inhibitor is strongly associated with the reactivation of latent tuberculosis into secondary tuberculosis." (PMID 25317081, 2014). "Given the importance of TNFα in IBD pathogenesis, the increasing use of anti-TNFα therapy to control the disease, and the risk of tuberculosis associated with such therapy, it will be important to determine if TNFα has inhibitory effects on hepcidin expression in human IBD." (PMID 22675442, 2012). "The risk of tuberculosis raises many questions about the safety of anti-TNF agents." (PMID 27536430, 2012). "We can conclude that TNF-857C/T genotype may be considered as a genetic marker that influences the susceptibility to tuberculosis in studied Iranian populations." (PMID 22737473, 2011). "However, as the present study was performed with relatively small sample size, further studies with larger sample sizes would be necessary to elucidate the role of TNF polymorphisms in tuberculosis." (PMID 20537163, 2010). "In addition, tumor necrosis factor inhibitors alleviate symptoms of RA while simultaneously increasing the risk of infection from tuberculosis, Myobacterium marinum tenosynovitis, fungal infection, and other opportunistic infections." (PMID 20808933, 2010). "Thus, our findings exclude the TNF genes as major risk factor for tuberculosis in the North Indians." (PMID 20537163, 2010). "Thus, patients with tuberculosis who lack adequate TNF-α production are at risk for disseminated, rapidly progressing and unusual presentations of tuberculosis." (PMID 19830122, 2009). "Another well-known side effect of anti-TNFα drugs is an increased risk of tuberculosis (TB) development." (PMID 41481132, 2026). "Certain psoriatic disease treatments, including tumor necrosis factor-α inhibitors (TNFi), increase tuberculosis (TB) risk." (PMID 42226468, 2026). "The risk of reactivation of tuberculosis by TNF inhibitors is a generally recognized consequence of this type of treatment and may limit the use of these drugs, particularly in countries where tuberculosis is endemic or in people with a history of tuberculosis." (PMID 40806803, 2025).
tuberculosis (continued). "Although the number of patients receiving anti-TNF treatment in our study was small, we observed that, in daily practice, the number of such patients is considerably higher, and this frequently used drug group requires close monitoring because of its increased risk of developing active tuberculosis." (PMID 40629593, 2025). "Patients living with rheumatologic diseases on disease-modifying antirheumatic drugs (DMARD) are at an increased risk of developing tuberculosis (TB), particularly with TNF-alpha inhibitors." (PMID 38959249, 2024). "Together, these findings suggest that the TNF genotype is causal for the TB phenotype after exposure to M. tuberculosis." (PMID 39198650, 2024). "In addition to TNF- α, increased Interleukin-6, Interleukin-8, and Interleukin-12(IL-6,8 and 12) levels have been linked to the formation of cavities, bronchial wall thickening, and fibrotic bands in individuals with active tuberculosis." (PMID 37303367, 2023). "Some cytokines resulting from the activation of T lymphocytes and phagocytic cells, such as IFN-γ and TNF-α, are efficient in controlling infection, while others may contribute to the survival and growth of Mtb or mediate susceptibility to tuberculosis, including IL-4, TGF-β, and IL-10." (PMID 37892223, 2023). "The association between TNF blockade and tuberculosis (TB) has been established in the early stage of biologic therapy." (PMID 35761359, 2022). "Patients receiving anti-TNF therapy are at risk of developing tuberculosis (TB), usually due to the reactivation of a latent TB infection (LTBI)." (PMID 35807201, 2022). "However, TNF-α inhibitors may also cause serious adverse reactions, such as inactivation of tuberculosis during incubation, and increased risk of certain malignant tumors." (PMID 33613635, 2021). "Both randomized controlled trials (RCTs) and real-world studies have implicated tumor necrosis factor inhibitors (TNFis) as increasing the risk of tuberculosis (TB), particularly in patients with a pre-existing latent tuberculosis infection (LTBI)." (PMID 34504225, 2021). "The use of biologics and anti-tumor necrosis factor drugs (anti-TNF) is associated with an increased risk of infections including tuberculosis (TB), and possibly viral hepatitis B (HBV) and viral hepatitis C (HCV)." (PMID 32740672, 2021). "One of the shortcomings of bDMARDs, especially TNF-α inhibitors, is the risk of developing tuberculosis (TB)." (PMID 34831081, 2021). "Tuberculosis (TB) is one infection associated with anti-TNF therapy, which is thought to inhibit the formation of granuloma and thus prevent the suppression of TB activation." (PMID 34670529, 2021). "There is an increased risk of TB activation associated with treatment by TNF-α inhibitors, illustrating the importance of TNF-α in containing Mycobacterium tuberculosis infection." (PMID 31862768, 2020). "Together, these data underline the TNF gene as an immune regulator of antibodies in TB, also they provide mechanistic insights into the function of antibodies in controlling M. tuberculosis infection." (PMID 32742607, 2020). "In multivariate analysis, contact age < 15 years, US/Canadian birth, and IFN or TNF concentrations > the median were associated with co-prevalent tuberculosis (P < .01 for each); female sex (P = .03) and smoking (P < .01) were associated with incident tuberculosis." (PMID 32736606, 2020). "Notably, anti-TNF-α therapies are immunosuppressive and, thus, may cause reactivation of latent infection, e.g., tuberculosis and hepatitis B." (PMID 33003495, 2020). "Tumor necrosis factor (TNF) antagonists are highly effective but associated with increased risk of tuberculosis (TB), mostly due to reactivation of a latent infection." (PMID 32459801, 2020). "Interfering with the involvement of TNF on granuloma formation, anti-TNF agents increase the risk of developing tuberculosis (TB)." (PMID 28146077, 2017).
tuberculosis (continued). "In order to understand the reasons underlying the increased risk of TB development among patients treated with anti-TNF drugs, it is necessary to analyze mechanisms of immune response to Mycobacterium tuberculosis." (PMID 28146077, 2017). "However, the safety and optimal timing for reinitiating TNF inhibitor in patients with active tuberculosis associated with previous or concurrent use of TNF inhibitors are unknown." (PMID 27101309, 2016). "Some evidences exist about a high risk of developing active tuberculosis (TB) in patients with latent TB infection undergoing anti-TNF-α therapy as well as the development of NTM disease during this therapy." (PMID 26106603, 2015). "However, excessive production of TNF is also associated with higher susceptibility to tuberculosis." (PMID 24973749, 2014). "Overexpression of mir3179 has been implicated along with slightly altered TNF and IL-6 levels in Tuberculosis (TB) group compared to controls." (PMID 24587348, 2014). "It is known that patients receiving immunosuppressive agents such as prednisone or TNF-α blockers are at increased susceptibility to TB upon exposure; these individuals also have a higher risk of reactivation of M. tuberculosis once infected." (PMID 23320160, 2012). "In this respect, it has been shown that TNFα blockade can cause reactivation of tuberculosis (TB) in animal models, and it has also been suggested that inhibition of TNFα in patients with chronic hepatitis B infection (HBV) could worsen the disease, since TNFα is involved in viral clearance." (PMID 21494611, 2011). "TNF-neutralizing drugs used to treat inflammatory disorders have been reported to increase the risk of tuberculosis (TB), in accordance with animal studies." (PMID 17953477, 2007). "TNF neutralising therapies for rheumatoid arthritis and Crohn's disease turned out to increase the risk of developing tuberculosis (TB) and other opportunistic infections." (PMID 16285886, 2005). "In Spain, patients with RA treated with anti-TNF-α medicines experienced a significant decrease in their chance of getting active tuberculosis after national recommendations were released." (PMID 40621538, 2025). "utilized machine learning techniques and found that among HIV-positive patients, those with tuberculosis exhibited significantly elevated levels of inflammatory markers including IL-2, IL-4, IL-6, IL-10, TNF-α, and IFN-γ." (PMID 41322408, 2025). "KEGG analysis results indicate that the up-regulated genes in CFG were primarily involved in IL-17 signaling pathway, TNF signaling pathway, and some microbial-like reactions (such as salmonella infection, viral protein interaction and tuberculosis)." (PMID 40594253, 2025). "In tuberculosis, TNF-α is essential for granuloma formation, limiting M. tuberculosis growth and multiplication." (PMID 40141021, 2025). "This review systematically analyzes over 300 peer-reviewed studies published between 1980 and 2024, highlighting the molecular and cellular mechanisms of TNF action in tuberculosis (TB)." (PMID 40427602, 2025). "Some biological agents, especially tumor necrosis factor (TNF)-antagonists and Janus kinase (JAK) inhibitors lead to a substantial risk of tuberculosis reactivation in individuals with M. tuberculosis infection." (PMID 40823191, 2025). "We report a rare case of non-articular osseous sarcoidosis with progressive pulmonary lesions and persistently normal inflammatory biomarkers (ACE, CRP, ESR, IL-2, and TNF-α) that required differentiation from metastatic bone tumors and tuberculosis." (PMID 40361953, 2025). "Except for adalimumab, the other three TNF-α inhibitors showed positive signals related to infective pneumonia, with tuberculosis-related diseases being the most common infections." (PMID 40763141, 2025). "Serum levels of IFN-γ, TNF-alpha, and IL-10 were significantly elevated before treatment in tuberculosis patients and decreased significantly post-treatment." (PMID 40276432, 2025).